NUP37 (nucleoporin 37)
Diseases named in the same sentence as NUP37 in open-access papers (continued):
Sharing a sentence is not in itself a finding about the gene and the disease.
oral cancer (2 papers, 2022 to 2025). "Hub genes VRK1, NUP37, HMMR, SPC25, and RUVBL1 were identified to be related to oral cancer at both molecular level and clinical levels." (PMID 36052378, 2022).
glioblastoma (1 paper, 2021). The most malignant astrocytic tumor (WHO grade IV). "Therefore, to remedy such a flaw, we collected tissue samples from 23 glioblastoma cases and corresponding clinical information to further explain the influence of the NUP37 on glioblastoma prognosis." (PMID 34264013, 2021).
Intellectual disability (1 paper, 2021). "However, mutations in NPC subunit component nucleoporin 37 (NUP37) also exhibit intellectual disability and MCPH." (PMID 35111754, 2021).
oral squamous cell carcinoma (1 paper, 2017). "Previous study has shown the NUP37 is both a significant mutated genes and a tumor-destructive genes in oral squamous cell carcinoma, suggesting that NUP37 might function in the tumorigenesis." (PMID 29228669, 2017).
pancreatic cancer (1 paper, 2023). "Notably, the only independent protective factor WDR37 was low expression in pancreatic cancer, and the only independent risk factor NUP37 was high expression in pancreatic cancer." (PMID 38304253, 2023).
cancer (14 papers, 2017 to 2024). A tumor composed of atypical neoplastic, often pleomorphic cells that invade other tissues. "NUP37, a component of the nuclear pore complex, is both a significantly mutated gene and a tumor-destructive gene in various carcinomas." (PMID 34422815, 2021). "Previous studies have shown that increased NUP37 expression in HCC acts as a positive regulator of Yes-associated protein 1/TEA domain family member (YAP1/TEAD) signaling, thereby promoting cancer progression." (PMID 39080077, 2024). "Tumor tissues with high NUP37 expression exist in a relatively immunosuppressive microenvironment and are resistant to several anti-cancer drugs." (PMID 35093934, 2022). "First, the research explored the conveying of NUP37 about 31 tumor types with corresponding inform tissue employing the Cancer Genome Atlas and Genotype-Tissue Expression data." (PMID 35093934, 2022). "Here, we evaluated the expression, methylation, copy number alteration, and prognostic significance of NUP37 using RNA-seq and clinical data from The Cancer Genome Atlas." (PMID 35093934, 2022). "IHC staining of HCC tissue samples showed that MCM2 and NUP37 were mainly expressed in nucleoplasm of carcinoma cells." (PMID 35093119, 2022). "Taken together, our results demonstrated that LRP5 bound to and modulated the stability of NUP37, thereby maintaining the dynamic integrity of NPCs and subsequently promoting cancer progression in HCC." (PMID 31881970, 2019). "This is the first study which examined the physical and functional interaction between LRP5 and NUP37 in cancer." (PMID 31881970, 2019). "Among the 208 confirmed genes, mutations in NUP37, C18orf8, and BBS12 were detected in 2 cancer tissues." (PMID 30375428, 2018). "This study was the first to assess the expression of NUP37 pan-cancer." (PMID 35093934, 2022). "The results suggested that invalids who have high NUP37 expression might resist to some anti-cancer drugs, such as PF-4708671 and GSK269962A, at the same time have sensitive to most anti-cancer drugs, such as MK-1775 and erlotinib." (PMID 35093934, 2022). "It has been said NUP37 can regulate the growth and death of cancer cells." (PMID 35093934, 2022). "The patients with the evaluated expression of NUP37 were resistant to several anti-cancer drugs." (PMID 35093934, 2022). "NUP37 expression was positively associated with the infiltration levels of immunosuppressive cells, such as nTregs, iTregs, and tumor-associated macrophages, and negatively correlated with immune killer cells, such as CD8+ T and NK cells across cancers." (PMID 35093934, 2022). "In addition, we assessed the NUP37 mutation, CNA and methylation conditions in the cancer pan." (PMID 35093934, 2022). "At last, we analyzed the correlation between NUP37 and half-maximal inhibitory concentration (IC50) of 192 anti-cancer drugs using the Genomics of Drug Sensitivity in Cancer (GDSC) database." (PMID 35093934, 2022). "In the study of tumor cell lines, it is necessary to use the data of the Cancer Cell Encyclopedia (CCLE) database to study, and it is found that NUP37 has the highest expression in MESO cell line." (PMID 35093934, 2022). "Over the past decades, several key regulators were revealed to modulate cancer cell proliferation, cell cycle, and apoptosis in NSCLC, such as NUP37, ARHGAP24, and PTEN." (PMID 34351079, 2021). "Recent studies have shown that upregulated expression of NUP37 in HCC acts as a positive regulator of YAP/TEAD signaling, thereby promoting cancer progression." (PMID 31881970, 2019). "Over-expression of NUP37 in 7404 and PVTT cells promoted the growth, migration, colony formation and invasion of cancer cells." (PMID 29228669, 2017). "Collectively, these data suggested that NUP37 promoted the progression of HCC by enhancing the growth, migration, colony formation and invasion of cancer cells." (PMID 29228669, 2017). "The role of NUP37 has rarely been reported in cancer cells and has never been studied in BRCA previously." (PMID 34386417, 2021).
cancer (continued). "Moreover, expression of the cancer stem cell surface marker CD44+CD24-/low subpopulation, which is measured by flow cytometry and mammosphere forming efficiency, was also reduced after NUP37 downregulated." (PMID 34386417, 2021).
tumor (10 papers, 2013 to 2025). "Higher expression of MCM2 or NUP37 was significantly associated with advanced tumor stage and worse overall survival in 3 large independent HCC cohorts (n = 820)." (PMID 35093119, 2022). "Meanwhile, correlation analyses of MCM2 or NUP37 expression with clinicopathological features revealed a significant association between NUP37 overexpression and tumor metastasis." (PMID 35093119, 2022). "A prognostic risk model incorporating NUP37, PGM2L1, and ENO1 effectively predicted patient outcomes, highlighting these genes’ roles in tumor progression." (PMID 40507914, 2025). "The results revealed that the subcutaneous tumor volume in the experimental group (shNUP37), in which the NUP37 gene was stable low expression, was smaller than that in the control group (shCtrl) on the 12th, 15th, and 19th days of measurement, respectively." (PMID 39174498, 2024). "Nup37, a constituent of the Nup107 sub-complex in yeast, has been observed to possess tumor-suppressive properties in oral squamous cell carcinoma." (PMID 39174498, 2024). "We observed higher expression of NUP37 in 28 of 29 tumor types, and high NUP37 expression predicted worse survival status of patients in 15 tumors." (PMID 35093934, 2022). "Consistently with the expression profiles in omics datasets of HCC, validation by western blot and RT-PCR in 10 pairs of human HCC tissue samples showed that MCM2 and NUP37 were significantly upregulated in HCC relative to the paired peri-tumor samples." (PMID 35093119, 2022). "We further assessed the role of NUP37 in the tumor immune microenvironment using immune infiltration data." (PMID 35093934, 2022). "The results showed that in LGG, NUP37 showed the same changes as immune score, matrix score and estimated score, but was opposite to tumor purity." (PMID 35093934, 2022). "Nucleoporin 37 kDa (NUP37), a member of the nucleoporin family, has been reported to regulate the proliferation and apoptosis of several tumor types." (PMID 35093934, 2022). "In conclusion, we finally identified five genes most associated with tumor progression and prognosis: VRK1, NUP37, HMMR, SPC25, and RUVBL1." (PMID 36052378, 2022). "On the research we evaluated and assessed NUP37 conveying in tumor tissues of the TCGA cohort and considered NUP37 was most greatly expressed in TGCT and lowly expressed in UVM." (PMID 35093934, 2022). "Then, in ACC, KIRC, RABRC, LUAD, LUSC and UCS, NUP37 were higher in the initial stage of tumor." (PMID 35093934, 2022). "The mRNA expression profiles of MCM2 or NUP37 stratified by the tumor stage showed that MCM2 (Stage II vs. Stage I, p < 0.05; Stage III vs. Stage I, p < 0.001) or NUP37 (Stage II vs. Stage I, p < 0.05; Stage III vs. Stage I, p < 0.05) expression was significantly increased in advanced tumor stage." (PMID 35093119, 2022). "Finally, Kaplan-Meyer OS analysis concluded that the increased expression of NUP37 indicated that the OS of patients with 15 tumor types was poor, including GBM and LGG." (PMID 35093934, 2022). "Similarly, the MCM2 and NUP37 protein levels in HCC tissues are significantly higher than that in peri-tumor tissues from NODE proteomics dataset." (PMID 35093119, 2022). "In addition, multivariate survival analysis showed that tumor size > 5.6 cm, advanced tumor stage, ALT > 25U/L, MCM2 or NUP37 overexpression were independent risk factors for worse OS of HCC patients." (PMID 35093119, 2022). "However, knocking down the expression of NUP37 inhibited the tumor formation in other lobes." (PMID 29228669, 2017). "To determine the clinical relevance of MCM2 or NUP37 overexpression in human HCC, we firstly investigated the correlation between tumor stage (TNM stage) and MCM2 or NUP37 overexpression using TCGA samples." (PMID 35093119, 2022).
NUP37 also shares sentences with these, for which no sentence is quoted: autoimmune disease (1 paper); autosomal recessive primary microcephaly (1); brain glioma (1); cervical squamous cell carcinoma (1); colon adenocarcinoma (1); COVID-19 (1); diffuse large B-cell lymphoma (1); endocervical adenocarcinoma (1); inflammatory bowel disease (1); lymphoid neoplasm (1).